CAV1 (caveolin 1)
Diseases named in the same sentence as CAV1 in open-access papers (continued):
Sharing a sentence is not in itself a finding about the gene and the disease.
cancer (continued). "The purpose of our study was to ascertain whether the stromal and cancer cell CAV1 expression in colorectal liver metastases affects the disease-free survival (DFS) and overall survival (OS) of patients with liver-only colorectal metastases undergoing hepatectomy." (PMID 28515480, 2017). "Recently, Cav-1 has been demonstrated to be closely involved in tumorigenesis and development, affecting the proliferation, survival, apoptosis, migration, invasion, metastasis, autophagy, transformation, anoikis, and chemotherapy resistance processes of cancer cells." (PMID 28546853, 2017). "With regard to the CAF model, patient-derived normal and according cancer-associated fibroblasts revealed a conserved gene expression, defined by increased transcript levels of ACTA2, COL1A1, TNC, VEGFA and ALDH1A3, with concomitant decreased expression of CAV1, CD44 and VIM in CAFs." (PMID 28372546, 2017). "Therefore, Cav-1 may be a target of antioxidants in oxidative stress modulation and cancer antioxidant prevention." (PMID 28546853, 2017). "Indeed, some researchers found that caveolin-1 is present in isolated extracellular vesicles from cancer cells, suggesting that caveolin-1 may contribute to the formation of extracellular vesicles." (PMID 29181124, 2017). "However, when cancer progresses into the advanced stage or are treated with cytotoxic agents, the expression of Cav-1 would be upregulated to protect cancer cells escaping from death by speeding aerobic glycolysis, increasing stem cell population or overexpressing ABC transporters." (PMID 28546853, 2017). "We reasoned that restricted tissue availability of anti-neoplastic drugs during chemotherapy might expose cancer cells to sub-therapeutic concentrations, which activate signaling pathways and the expression of CAV1 to favor the acquisition of more aggressive traits." (PMID 29340103, 2017). "However, dysregulation of caveolin 1 expression is found in multiple types of cancer." (PMID 27973397, 2016). "CAV1 level may determine the effect of lipid load on cancer cells." (PMID 27852311, 2016). "Moreover, Cav-1 has been observed to be up- or down-regulated in various types of cancers." (PMID 27764093, 2016). "It will also be interesting to determine whether differential expression of CAV1 influences the expression or function of fatty acid enzymes that have recently emerged to be important mediators in cancer, e.g. acyl-CoA synthetase, carnitine palmitoyltransferase 1C, and carnitine acyltransferase." (PMID 27852311, 2016). "Therefore, we hypothesized that the post-translational modification of CAV1 might contribute to the emergence of MDR in cancer cells." (PMID 26843476, 2016). "The fact that CAV1 could serve as a clinical biomarker further emphasizes its importance in cancer." (PMID 27852311, 2016). "Indeed, studies in cancer and normal cells show that CAV1 modulates insulin signaling." (PMID 27852311, 2016). "Thus, targeting Cav-1 may offer a novel strategy for preventing cancer drug resistance and improving clinical outcomes." (PMID 26431273, 2015). "Therefore, we were interested in whether the reduction of Cav1 contributes to the change of cell mechanics in cancer cells." (PMID 26189182, 2015). "The hybridization of Cav-1-null mice with a spontaneous cancer model may be helpful." (PMID 26431273, 2015). "Interestingly, the CaV1 blocker, nifedipine, has been implicated in the proliferation of certain cancers, however, its effects are likely not mediated by blocking CaV channels." (PMID 26010603, 2015). "The expression level of Cav-1 in cancer cells might also be a variable." (PMID 25374561, 2014). "Furthermore lower caveolin-1 expressions were reported in some human malignant tumors." (PMID 25015569, 2014). "Moreover, hypermethylation of the CAV1 promoter in human cancer has also been shown." (PMID 25313138, 2014).
cancer (continued). "Caveolin-1 and flotillin-1 are considered as markers of lipid rafts which can be regarded as sorting platforms for targeted transport of transmembrane proteins and are involved in fundamental cellular events such as signal transduction, cell adhesion, lipid/protein sorting, and human cancer." (PMID 25243186, 2014). "Such initial discoveries lead to the proposal that Cav-1 may serve as a cancer prognostic factor." (PMID 25202343, 2014). "However, the relationship between Cav-1 expression and cancer progression remains unclear at both the cellular and molecular levels." (PMID 24949874, 2014). "Therefore, contradictory roles of Cav-1 expression in human cancer cells have been reported." (PMID 25202343, 2014). "Additionally, in terms of cancer cell migration, Cav-1 protein is shown to be a positive regulator." (PMID 24967418, 2014). "To date, the mechanism of overexpression of Cav-1 in cancer remains unclear." (PMID 24454730, 2014). "Furthermore, CAV1 contributes to metastatic phenotype in different types of carcinomas." (PMID 25180681, 2014). "Thus, our study revealed the existence of a novel mechanism of cancer cell adhesion regarding Cav-1 which might be exploited in metastasis and drug design." (PMID 23460862, 2013). "Therefore, it is possible that Cav-1 protein may function to regulate redox status of the cancer cells during metastasis." (PMID 23460862, 2013). "However, it remains unknown whether Cav-1 regulates ROS level in detached cells and such regulation is critical for cancer adhesive property." (PMID 23460862, 2013). "Also, Cav-1 may decrease the adhesive property of the cancer cells by attenuating hydrogen peroxide and hydroxyl radical." (PMID 23460862, 2013). "Moreover, Cav1 may affect cancer cell adhesion by modulating E-cadherin (E-cad), which is a major component of adherens junctions." (PMID 23521716, 2013). "Moreover, further clinical trials will be essential to verify the prognostic value of CAFs Cav-1 in GC and whether it could contribute to personalized anti-cancer treatment." (PMID 23527097, 2013). "Distinct non-caveolar functions of caveolin-1 will also have implications for our understanding of cancer development and progression since caveolin-1 mutation or overexpression is suggested to be involved in several cancers." (PMID 22912783, 2012). "Furthermore, the introduction of caveolin-1 scaffolding domain inhibits cancer progression." (PMID 21660237, 2011). "However, re-expression of Cav-1 at later stages of cancer may provide a protective mechanism for cancer cells to survive various harsh conditions such as DNA damage." (PMID 20700465, 2010). "A better understanding of the mechanisms responsible for determining where caveolin-1 is found in a cell and how variations in this distribution pattern impact on cell function is likely to help in defining the contribution of this protein to human disease states including cancer." (PMID 18400052, 2008). "Furthermore, it has been suggested that Caveolin-1 may contribute to certain steps of carcinogenesis in various types of cancer." (PMID 17915016, 2007). "Cancer cells are defined as cells expressing high MKI67, CAV1, and CTNNB1 and present spatial variations in the expression of VEGFC, FN1, and NRP1." (PMID 40081369, 2025). "The phosphorylation-dependent interaction of scaffolding protein caveolin-1 (Cav-1 Y14) inhibits the entry of Mfn2 and Drp1 to the mitochondria and the creation of the PINK1/Mfn2/Parkin complex in cancer cells." (PMID 40148800, 2025). "We propose a mechanistic model in which dual targeting of CAV1 and AXL impairs the pro-survival signalling via STAT3, AMPKα, and RAC pathways, thereby promoting excessive autophagy and inducing cancer cell death to overcome TKI resistance in HCC." (PMID 40715090, 2025). "Cav‐1 regulates TGF‐β/Smad signaling pathways, which are essential for the development of tissue fibrosis and the progression of cancer." (PMID 40778471, 2025).
cancer (continued). "This suggests that the upregulation of COL11A1 and the downregulation of CAV1, CXCL12, and SPTBN1 in the cancer microenvironment led to the downregulation of IL-6 and IL-33." (PMID 40898538, 2025). "Blocking Ago2/CAV1 interaction in cancer cells with P2 peptides decreased the migration and invasion of A549 cancer cells and HCC1806 cancer cells (Fig. 4Eii) in Boyden chambers." (PMID 38649663, 2024). "A549Ago2-KO/AID-Ago2Wt/Ago2∆ cancer cells were subcutaneously implanted into SCID mice, and the mice were injected with phosphate-buffered saline (PBS) or IAA for disruption of Ago2/CAV1 interaction." (PMID 38649663, 2024). "Disruption of Ago2/CAV1 interaction by P2 peptides resulted in the disassociation of Ago2 and other RISC proteins, GW182 and Dicer, from the membranes of cancer cells." (PMID 38649663, 2024). "We identified in the current study a unique interaction between Ago2 and CAV1, which can be regulated through lysine 212 acetylation in the CBM of Ago2, in cancer cells." (PMID 38649663, 2024). "Concerning CAV1, EFEMP1, FBLN2, TGFBI, or VDAC1, their actions are highly context-dependent and can vary across different cancer types and stages." (PMID 39201614, 2024). "Although there have been contradictory reports on the interaction between CAV1 and AKT, such as where CAV1 co-expresses with AKT leading to cancer progression, and others such as where CAV1 inhibits the AKT pathway." (PMID 37766164, 2023). "CAV1 expression has reportedly been correlated with decreased presence of PGE2 in the culture medium of HEK293T and colon (HT29(ATCC) and DLD1) cancer cell lines." (PMID 38069269, 2023). "Co-expressed genes (PXN, ITGA3, TES, and MET) were identified and analyzed by FunRich with CAV1 and CAV2, revealing a significant correlation with focal adhesion (p < 0.001), which has a vital influence on cancer progression." (PMID 36830672, 2023). "Cavelin-1 (Cav1) is located on the long arm of chromosome 7, and is localized at the D7S522 locus (7q31.1), which is a fragile site that is easily lost in cancer." (PMID 37910338, 2023). "Cav-1 can also promote the binding of epidermal growth factor receptor (EGFR) to the kinase domain of the Caveolin binding motif and act as a pro-cancer factor to activate EGFR-mediated mitosis initiation." (PMID 37828916, 2023). "We further explored the expression levels of CAVs in another independent data set (TIMER database) and validated that CAV1, CAV2, and CAV3 were expressed low in most cancer, especially in BC." (PMID 36147736, 2022). "Several upregulated genes (LRP1, SERPINA1, HRG, ILK, CAV1, and LAMA4) identified in our study are involved in GEM resistance in human cancer 23-28." (PMID 35281857, 2022). "Syntenin1 can prevent caveolin-1-mediated internalization and subsequent degradation of TGF-βRI, thus promoting TGF-β1-activated SMAD signaling and EMT in cancer cells." (PMID 36096985, 2022). "Tubeimoside V (TBMS-V) activated EGFR and ITGB1-FAK by regulating caveolin-1 (cav-1)-related signal pathway and finally made TNBC cancer cells sensitive to anoikis and inhibited TNBC cell growth and metastasis." (PMID 35414025, 2022). "TK1, TCN1, CAV1, and HS3ST2 play indispensable roles in survival predictions and pathogenesis of various cancers." (PMID 35898471, 2022). "MiR-96-5p targets CAV1 to restrain AKT phosphorylation and its down-stream Cyclin D1 and P70 protein levels, thereby facilitating cancer cell proliferation and migration." (PMID 36017148, 2022). "Caveolin-1 (CAV1) has previously been reported to play a major role in cellular senescence, but its effect on tumors depends on the cancer type." (PMID 35971182, 2022).
cancer (continued). "Cav-1, which is increased significantly in RCC kidney tissue, can regulate the growth and metastasis of cancer cells." (PMID 34955837, 2021). "The analysis of mRNA sequencing data from Cancer RNA-Seq Nexus (CRN) database revealed these genes in all stages showed a fold change higher than 2, except for CAV1 in Stage III and Stage IV A." (PMID 33739025, 2021). "Thus, further investigation of epithelial-stromal CAV1 functions as well as the identification of decisive CAV1 downstream targets may allow to characterize and in turn modulate the sensitivity of epithelial tumors to cancer therapy." (PMID 33868995, 2021). "More specifically, some authors have been able to show the importance of constitutive proteins from lipid rafts, such as the caveolin-1 (Cav-1) protein, in the early activation phase induced by VEGF in cancer models." (PMID 34205419, 2021). "For example, Cav-1 has been shown to facilitate both ERK and AKT signalling in cancer cells derived from prostate and colon, and is associated with promoting cell invasion, proliferation, angiogenesis and multi-drug resistance." (PMID 34490102, 2021). "Caveolin-1 (Cav-1), a membrane/lipid raft (MLR) scaffolding protein regulates metabolic pathways in several different cell types such as hepatocytes and cancer cells." (PMID 34572135, 2021). "Recently, clinical studies asserted a positive correlation between caveolin-1 expression, MVD, and poor prognosis in HCC and prostate cancer patients." (PMID 32676485, 2020). "Altered expression of caveolin-1 (CAV1) and autophagy marker ATG4C is observed in various types of human cancers." (PMID 32401768, 2020). "However, degradation of Cav‐1 can increase autophagy markers, such as cathepsin B (active form), lysosomal‐associated membrane protein‐1, LC3B, beclin 1, autophagy‐related 16 like 1, (ATG16L1), and BCL2 interacting protein 3 (BNIP3), to increase autophagy of cancer cells." (PMID 32508059, 2020). "The potential role of CAV1 and ATG4C in the formation and progress of cancers deserve further exploration." (PMID 32401768, 2020). "High expression of CAV1 protein in the stroma and ATG4C protein in cancer cells were found to be significantly related to the histologic subtypes of EOC patients (P = 0.019, P = 0.005, respectively)." (PMID 32401768, 2020). "Thus, here, we will review in detail the literature available on the role of CAV1 in cancer and specifically the canonical and non-canonical functions of the proteins associated with CAV1 at the plasma membrane and in other subcellular localizations, respectively." (PMID 32458269, 2020). "Cancer targeted nanoprobes were either adsorbed (AMD3100 targeting CXCR4 and Diadzein targeting Caveolin-1) or chemically crosslinked (folic acid targeting folate receptor) to the surface of the albumin nanocomposites." (PMID 33172421, 2020). "Among three known caveolins (CAV-1, 2 and 3), caveolin-1 (CAV-1) is ubiquitously expressed in all cell types and was found to be over-expressed in numerous cancers in which it can act as a positive regulator of stress resistance and survival." (PMID 32939172, 2020). "Hereby, the CaV1 inhibitor BK10040 was reported to reduce proliferation and induce apoptosis in cancer cells such as A459 (lung adenocarcinoma) and MiaPaCa2 (pancreatic cancer cells) cell lines." (PMID 32575381, 2020). "In conclusion, this is the first study that evaluates the clinical significance and prognostic value of CAV1/ATG4C for EOC patients, as well as their expression and distribution in both cancer cells and stromal cells." (PMID 32401768, 2020).
cancer (continued). "All 95 EOC samples were available for analysis of CAV1 and ATG4C immunostaining in cancer cells, of which 79(83.2%) cases had sufficient tissues for analysis of CAV1 and ATG4C immunostaining in stromal cells." (PMID 32401768, 2020). "ACAT-1 inhibition was reported to lead to down-regulation of the caveolin-1/MAPK pathway, which contributed to reduced cancer aggressiveness." (PMID 31978092, 2020). "In recent years, considerable attention has focused on Caveolin-1 (CAV-1), a key scaffolding/signaling protein, in driving cancer progression and metastasis." (PMID 32733649, 2020). "Consistently, Caveolin-1 and translocation of HMGB1 significantly and consistently suppress cancer cell migration and invasion, with little effect on cell viability." (PMID 31284269, 2019). "It has also been reported that upregulation of Cav-1 is related to the EMT and influences cancer cell motility." (PMID 31297035, 2019). "Our data indicate that increased Cav-1 in PCa cells by either gene transfection or TDE delivery can increase CSC phenotypes in vitro and along with elevated cancer-initiating activity in vivo." (PMID 31685812, 2019). "Further studies should be investigated to reveal the connecting mechanism between Cav-1 and the EMT, as well as cancer progression in NSCLC." (PMID 31297035, 2019). "For example, CAV1 is up-regulated after induction of EMT and upon expression enhances cancer cell adhesion." (PMID 31362353, 2019). "Previous studies have reported that up-regulation of Cav-1 is related to epithelial-mesenchymal transition (EMT) and influences cancer cell motility." (PMID 31297035, 2019). "CAV1-depleted NCIN87 and BT474 cancer cells showed increased in vitro ADCC when PBMCs were used as effector cells (E:T ratio = 50:1)." (PMID 30510281, 2018). "Caveolae are caveolin-1 (CAV1) enriched subdomains of the plasma membrane, which are deregulated in cancer cells and contain a high content of cholesterol and sphingolipids." (PMID 30510281, 2018). "Decreased Cav-1 levels correlate with higher levels of the monocarboxylate transporter-4 (MCT4) in the stroma and of the lactate transporter (MCT1) in cancer epithelial cells." (PMID 30486451, 2018). "Caveolin-1 (CAV1) is located on chromosome 7q31.2 at the D7S522 locus, a fragile point known to be deleted in certain human cancers." (PMID 30005686, 2018). "Oxidative stress induced by cancer cells has been proposed to activate pro-autophagic factors like HIF-1α and NF-κB, inducing an autophagic/lysosomal degradation of caveolin-1 (Cav-1)." (PMID 30486451, 2018). "We propose this CAV1-YAP regulation has important implications in the progression of some pathologies, such as cancer, and will allow us to better understand the principles governing processes driven by substrate stiffness in health and disease." (PMID 30404014, 2018). "When engineered Jurkat cells were used as effector cells, CAV1 depletion in NCIN87 and BT474 cancer cells resulted in a decrease in IC50 values (E/T = 15:1)." (PMID 30510281, 2018). "However the potential re-distribution of Cav1 we observed in vivo when we attempt to mimic the human situation by implanting Cav1(−) PC3 cells (as prostate epithelial cells were Cav1-negative when the cancer develops) coincides with increased radiation resistance." (PMID 28112237, 2017). "The CAV-1 gene resides on chromosome 7q31.1, a fragile site known as FRA7G, which is commonly deleted in human cancers." (PMID 28828003, 2017). "Contrastingly, proteins that promote cell adhesion such as Paxillin (PXN), breast cancer anti-oestrogen resistance 1 (BCAR1) and Caveolin-1 (Cav-1) were upregulated." (PMID 28217176, 2017). "Given this CAV1 connection to a more aggressive phenotype at later stages of cancer disease, we reasoned that treatment with cytotoxic drugs using conditions that may not induce cell death might in fact promote CAV1 expression and thereby favor cancer progression." (PMID 29340103, 2017).